CST3 (cystatin C)
Diseases named in the same sentence as CST3 in open-access papers (continued):
Sharing a sentence is not in itself a finding about the gene and the disease.
testicular cancer (1 paper, 2022). A primary or metastatic malignant neoplasm that affects the testis. "The authors compared eGFR based on serum creatinine and cystatin C levels in 53 patients with testicular cancer and showed that creatinine-based eGFR was significantly lower than cystatin C-based eGFR (p<0.05)." (PMID 36589819, 2022).
toxicity (1 paper, 2019). The degree to which an agent can damage an organism. "Moreover, eGFR, creatinine and cystatin C levels were not significantly changed 48 hours following the angiographic procedures, suggesting low kidney toxicity in this patient population." (PMID 31427688, 2019).
uremia (1 paper, 2019). A clinical syndrome associated with the retention of renal waste products or uremic toxins in the blood. "CKD creates a toxic vascular and metabolic milieu with substances such as homocysteine, uremic toxins, creatinine, and cystatin C that promote systemic inflammation, oxidative stress, uremia, and systemic vascular endothelial dysfunction." (PMID 31780807, 2019).
ureterocele (1 paper, 2023). A cystic and dysplastic dilation of the distal ureter within the bladder that may extend into the bladder neck and urethra. "Clinical data including age at diagnosis, body weight, history of UTI, ureteroceles, ectopic ureteral opening, VUR grade, serum creatinine level, cystatin C level, renal scarring, split renal function in dimercaptosuccinic acid scans, and effective renal plasma flow (ERPF) were analyzed." (PMID 36103043, 2023).
uric acid stones (1 paper, 2025). "Both creatinine-based estimated GFR (eGFRcrea) and serum cystatin C-based estimated GFR (eGFRcys) increase the risk of uric acid stones." (PMID 40551898, 2025). "We have revealed and validated the elevation of serum creatinine and serum cystatin C levels in patients with uric acid stones." (PMID 40551898, 2025). "Among the major stone categories, patients with uric acid stones exhibited elevated levels of serum creatinine and serum cystatin C. In urinary system stones, prostatic calculi were characterized by increased PSA and monocyte cell counts." (PMID 40551898, 2025).
varicocele (1 paper, 2025). A condition characterized by the dilated tortuous veins of the spermatic cord with a marked left-sided predominance. "Clinical study have found that infertile oligoasthenoteratozoospermic men associated with varicocele have significantly higher cystatin C levels in semen than healthy males." (PMID 40331931, 2025).
ventricular fibrillation (1 paper, 2018). A disorder characterized by an electrocardiographic finding of a rapid grossly irregular ventricular rhythm with marked variability in QRS cycle length, morphology, and amplitude. "Therefore we also determined that cystatin C might be more sensitive for smaller changes in renal function and has been shown to be strongly significantly correlated with the histopathological grade of renal injury in an animal model of ventricular fibrillation CA." (PMID 29884198, 2018).
vitamin B12 deficiency (1 paper, 2024). A disease characterized by low serum levels of vitamin B12, either inherited or acquired. "Major complications occurred more often in individuals with significantly increased cystatin c levels (31 individuals, 25%), calcium deficiency (9 individuals, 31%), normal HbA1c levels (5 individuals, 36%), and with vitamin B12 deficiency (10 individuals, 40%)." (PMID 38123748, 2024).
yang deficiency (1 paper, 2022). Yang deficiency is a concept from traditional Chinese medicine. "In this study, the Cystatin C protein was found to be significantly upregulated in both Yang deficiency and Qi-yin deficiency patients." (PMID 35087594, 2022). "However, like CRP protein, Cystatin C also showed a higher induced level in Yang deficiency (upregulated by 2.3-fold) than in Qi-yin deficiency (upregulated by 1.4-fold) patients." (PMID 35087594, 2022).
kidney disease (193 papers, 2007 to 2026). "Vcam1 facilitates leukocyte recruitment in renal diseases, Apoe influences lipid metabolism and renal function risk, and Cystatin C acts as a biomarker for renal function, indicating impaired kidney function when elevated." (PMID 41567268, 2026). "Recent data shows that serum cystatin C in dogs is in fact correlated with age, weight and also significantly associated with cardiovascular or renal disease-related death." (PMID 41008005, 2025). "On the other hand, known commensal bacteria such Prevotella, Roseburia and Fecalibacterium prausnitzii that were depleted among kidney disease populations, were associated with a better kidney function (eGFR) and decreases in Cystatin C levels." (PMID 32503496, 2020). "Given its documented advantages in identifying subclinical kidney disease, cystatin C has constantly been used as a marker associated with cardiovascular events." (PMID 32962217, 2020). "Human cystatin C (hCC), a cysteine protease inhibitor, has been proposed as a diagnostic marker because its serum levels correlate with certain cardiovascular and kidney diseases." (PMID 26799562, 2016). "The present study extends prior investigations and supports the view that kidney disease approximated by elevated cystatin C is associated with concentric remodeling." (PMID 21977320, 2011). "The chronic inflammation in these dogs may cause increased cystatin C concentration even at an early stage of kidney disease, as was discovered in elderly humans." (PMID 41008005, 2025). "Furthermore, the study encourages the potential use of cystatin C-based measures for determining the presence of kidney disease in this high-risk group of PLWH, as previously highlighted." (PMID 39056083, 2024). "Cystatin C could be another factor related to renal function, owing to its function of removing metabolic waste products and its association with kidney disease." (PMID 36767787, 2023). "Increased serum cystatin C levels with normal creatinine levels indicate a subclinical kidney disease associated with a high risk of developing a clinically significant stage of kidney disease, leading to the early development of cardiovascular complications." (PMID 33456602, 2020). "Variants in Cystatin C (CST3), have been also shown to impact altered eGFR and kidney disease." (PMID 29665793, 2018). "This study will provide important data about the local epidemiology of kidney disease in a high-risk rural setting and the utility of emerging renal filtration markers (Beta 2 Microglobulin and Cystatin C), while generating data and methods for the analyses of microRNA biomarkers." (PMID 29486722, 2018). "Besides, cystatin C is known to be a sensitive marker of small reductions in renal function and has been shown to detect “preclinical kidney disease,” which is associated with increased risk of CKD progression and cardiovascular death." (PMID 24876964, 2014). "Whereas GWAS for creatinine and cystatin C levels in individuals with high serum creatinine (we will use the top1 set hereafter) identify loci associated with impaired kidney function because the serum levels of these two metabolites are both increased as a consequence of kidney disease." (PMID 39927731, 2025). "An increased prevalence of left ventricular hypertrophy and systolic and diastolic dysfunction were found among patients with kidney disease, including those with elevated cystatin C concentrations, which could explain the increased risk of sudden cardiac death." (PMID 24982887, 2014). "Nonetheless, our study offers valuable insights into the potential benefits of using Cystatin C-based eGFR in diagnosing and managing renal disease in HIV-positive individuals, particularly highlighting the high precision of Cystatin C-based eGFR formulas." (PMID 38654183, 2024). "Initiatives to measure specific risk factors or biomarkers to include in algorithms instead of race (eg, cystatin C–based calculations for kidney disease) require increased support." (PMID 37266959, 2023).
kidney disease (continued). "Some factors were reported to be positively associated with kidney disease in pSS, including ANA, anti-SSA, anti-SSB, RF, low C3/C4, urea, creatinine, cystatin C, β2-microglobulin, etc.." (PMID 37735697, 2023). "This showed that the serum cystatin C level is related to subclinical tubular impairment and can be an earlier marker of renal disease in diabetic patients before the onset of other renal markers." (PMID 37082121, 2023). "NGAL, cystatin C and podocin show potential as biomarkers for kidney disease (including detecting kidney injury earlier than creatinine)." (PMID 36230418, 2022). "There is currently some but limited evidence on NGAL and cystatin C. However, these studies show strong potential for future use for both these biomarkers to diagnose kidney disease, including earlier detection of kidney disease than creatinine." (PMID 36230418, 2022). "Associations between serum or EDTA-plasma NfL and renal function (serum creatinine, serum cystatin C, glomerular filtration rate, and kidney disease) were investigated using linear or logistic regression, respectively." (PMID 35775045, 2022). "Serum cystatin C level is not only a sensitive marker for renal disease but also a predictive marker for CVD and inflammation." (PMID 36506069, 2022). "Cystatin C and podocin show potential as biomarkers for kidney disease (including detecting AKI earlier than creatinine) and should be studied further." (PMID 36230418, 2022). "As such, Cystatin C can offer advantages to diagnose kidney disease in situations where creatinine fails." (PMID 36230418, 2022). "As cystatin C is also a marker of kidney disease, we conducted a subgroup analysis in patients with normal kidney function, ie, eGFR of 90 mL/min/1.73m2 or greater (63 in the UK [33 STDR events] and 61 in India [38 STDR events])." (PMID 35511139, 2022). "This work interestingly finds cystatin C to be the most important biomarker in relation to kidney disease, with creatinine the second most important." (PMID 34209487, 2021). "eGFR using serum creatinine (eGFR-Cr) and eGFR using serum cystatin C (eGFR-CysC) were calculated using the new Japanese coefficient-modified Modification of Diet in Renal Disease study equation." (PMID 33972623, 2021). "Urinary Cystatin-C would be useful for subclinical kidney disease in the early stage where UACR fail to detect in the CKDu-affected area." (PMID 34795341, 2021). "In comparison, others have reported that urine cystatin C was barely detectable in the urine of most healthy cats and dogs, although present in most cats and dogs with renal disease." (PMID 34324590, 2021). "Serum cystatin C was broadly reported as a biomarker for renal dysfunction in LN and other renal diseases." (PMID 33108403, 2020). "Individuals with kidney disease (27%; cystatin C > 1.3 mg/L) had increased serum progranulin levels (74.32±20.8 ng/mL vs. 63.21±14.8 ng/mL, P < 0.001), which is consistent with previous findings." (PMID 32886731, 2020). "In order to evaluate the sensitivity of serum biomarkers for renal dysfunction in patients with known renal disease, receiver operating characteristic (ROC) curve was drawn for creatinine, cystatin C, α1-MG and various combinations of these." (PMID 33042142, 2020). "Cystatin C-based equations compared with creatinine-based formulae have been suggested to more precisely estimate GFR in black South Africans with early renal disease." (PMID 32854641, 2020). "Cystatin C has been proposed as an alternative marker for estimating the GFR in native kidney disease." (PMID 32725073, 2020). "This was likely because cystatin C reflected kidney disorder from an earlier stage compared to creatinine." (PMID 31490935, 2019).
kidney disease (continued). "Presence of renal disease was evaluated using each renal biomarker: creatinine, urea, cystatin C, eGFR and albuminuria." (PMID 29694626, 2018). "Previously, it has been shown that there is little overlap between well-validated SNPs for kidney disease and CHD, where only rs653178 was highly associated with both cystatin-C-based eGFR and CHD21." (PMID 27338949, 2016). "Middle molecules such as Cystatin C and β2-microglobulin accumulate in renal disease and plasma levels have been used to estimate kidney function early in this condition." (PMID 26629900, 2015). "It should also be mentioned that elevated cystatin C concentrations also capture preclinical kidney disease." (PMID 24982887, 2014). "We were able to accurately examine the association between estimates of GFR using the newly developed cystatin C equations and clinical outcomes in a population with a low prevalence of CVD and renal diseases, which further strengthens this association." (PMID 25265151, 2014). "Over the past, many reports highlighted the ability of cystatin C to detect renal disease early in different settings." (PMID 25215234, 2014). "Mean cystatin C concentration at baseline was 1.18 (±0.29) mg/L, and over the 5-year follow-up period, 60 (6%) of participants experienced a renal disease event." (PMID 23940710, 2013). "Six of these proteins (uromodulin, α-1-microglobulin, zinc-α-2-glycoprotein, cystatin C, Ig-kappa-chain, and inter-α-trypsin heavy chain H4) were strongly correlated with various forms of kidney disorders." (PMID 21997203, 2012). "Research including 18 253 human patients aged 28 to 100 years revealed that cystatin C levels were significantly higher in patients over 80 years without a risk of developing kidney disease than in patients under 40 years." (PMID 41008005, 2025). "However, the summarized literature remains limited, while further clinical studies are required to provide insights into the potential use of cystatin C as a biomarker for kidney disease in PLWH." (PMID 38566923, 2024). "Two US National Kidney Disease Organizations propose the more frequent use of both the GFR estimating equations with cystatin C and race-free equations, because those based on cystatin C involve smaller differences between race groups compared to GFR estimates based solely on creatinine." (PMID 39125705, 2024). "In 2012, the Kidney Disease Improving Global Outcomes (KDIGO) guideline recommended the measurement of cystatin C in adults with eGFRcr between 45–60 mL/min/1.73 m2, particularly in cases where other indicators of kidney damage are absent to validate the diagnosis of CKD." (PMID 39125705, 2024). "In fact, some of the included studies showed that the creatinine-based GFR was increased in PLWH taking tenofovir disoproxil fumarate-containing ART, perhaps indicating that the use of both cystatin C- and creatinine-based GFRs is vital to monitor the development of kidney disease in PLWH." (PMID 38566923, 2024). "Otherwise, the abundance of known commensal bacteria, including Prevotellaceae_UCG_001, Roseburia and Bifidobacteria, which were reduced among kidney disease populations, are related to improved kidney function (eGFR) and reductions in cystatin C levels, BUN and Scr25." (PMID 37993541, 2023). "Additionally, NGAL has shown promise as a marker for predicting severe kidney diseases, surpassing the performance of cystatin C." (PMID 37626956, 2023). "In the population-based cohort of subjects without a history of renal disease, we found a positive association between visceral adipose tissue and serum cystatin C and an inverse association with e-GFRcys." (PMID 37280396, 2023). "The levels of cystatin C substantially increased with age, even in the absence of clinical risk factors for kidney disorders." (PMID 38132490, 2023).
kidney disease (continued). "Cystatin-C may be a sensitive biomarker for early kidney disease detection, as well as a clinical flag to improve cardiovascular disease prediction and potentially decrease mortality." (PMID 36094936, 2022). "Cystatin C is elevated in patients with renal disease and may be a marker of cardiovascular disease." (PMID 35883416, 2022). "Multicentre cross-sectional studies have demonstrated that estimated glomerular filtration rate (eGFR) calculations, in particular the Modification of Diet in Renal Disease study (MDRD) equation can overestimate GFR when compared to cystatin C based GFR measurements in a Chinese cohort." (PMID 35226673, 2022). "Based on the available literature, the authors believe that cystatin C could hold potential as biomarker for kidney disease (including earlier detection of kidney disease compared with creatinine) and should be included in future studies." (PMID 36230418, 2022). "One of the most prevalent nonrenal influences in patients with kidney diseases is the use of glucocorticoids, which is frequently prescribed in immunologic kidney diseases and causes abnormal elevation of cystatin C." (PMID 35845935, 2022). "Evidence from longitudinal studies had shown that the CVD risk factors smoking, and systolic blood pressure, are associated with cystatin C, both in the presence and absence of kidney disease." (PMID 34588554, 2021). "Cystatin C (CysC) is often used to diagnose and monitor renal diseases." (PMID 34867811, 2021). "Shroom family member 3 (SHROOM3) also appeared to be very significant in our GAWS studies on cystatin C. It plays an important role in mammalian kidney development and human kidney disease including CKD and ESRD through estimated glomerular filtration rate based on creatinine (eGFRcrea)." (PMID 34899825, 2021). "Eighteen differentially expressed proteins were found to overlap between the CKD and post-transplant CKD groups including biomarkers of kidney disease (cystatin C, β2-microglobulin, and REN) and biomarkers of inflammation (CFD, IGFBP-2, PRSS 2, Chemokine Ligand 15 (CCL-15), and TNFRSF-1B)." (PMID 33888746, 2021). "Moreover, in logistic regression analysis, the association between increased BTP and AKI was dependent on previous renal disease, in contrast to what was found for serum cystatin C." (PMID 31940861, 2020). "Principal component 2 (PC2, orthogonal on PC1) explained 14.3% variance, with high negative loading reflected by ‘impaired glucose metabolism’ (HOMA and glucose (as well as leptin)) and high positive loading reflected by ‘kidney disease’ (creatinine and cystatin C (as well as HDL))." (PMID 32567553, 2020). "Variants of cystatin C (CST3) have been also shown to impact altered eGFR and kidney disease." (PMID 31534799, 2019). "The SCD hazard was doubled in participants with “pre-clinical renal disease” (defined as estimated glomerular filtration rate: eGFR >60 mL/min/1.73 m2 and Cystatin C level ≥1.0 mg/L) matched to those with unaltered renal function (defined as eGFR >60 mL/min/1.73 m2 and Cystatin C level <1.0 mg/L)." (PMID 32009970, 2019). "Moreover, cystatin C seems to offer more complete prognostic information than other markers of renal disease." (PMID 24478035, 2014). "Furthermore, the high mean serum cystatin C in this work is consistent with prior reports of increased burden of HIV-related kidney diseases in blacks." (PMID 23213527, 2012). "Cystatin C, a cysteine protease inhibitor secreted by all nucleated cells, is a novel serum marker for kidney disease that may better detect small changes in kidney function." (PMID 18681974, 2008). "The use of cystatin C as a clinical marker of renal function, given its relationship to adipose tissue, raises additional questions regarding the correct assessment of eGFR in healthy subjects and patients with renal disease, particularly in the obese individuals." (PMID 37280396, 2023).